WDR59 (WD repeat domain 59)
Description:
As a component of the GATOR2 complex, functions as an activator of the amino acid-sensing branch of the mTORC1 signaling pathway. The GATOR2 complex indirectly activates mTORC1 through the inhibition of the GATOR1 subcomplex. GATOR2 probably acts as an E3 ubiquitin-protein ligase toward GATOR1. In the presence of abundant amino acids, the GATOR2 complex mediates ubiquitination of the NPRL2 core component of the GATOR1 complex, leading to GATOR1 inactivation. In the absence of amino acids, GATOR2 is inhibited, activating the GATOR1 complex.
Synonyms: FP977; FLJ12270; CDW12; p90-120
Tractability: PROTAC: ubiquitination databases record sites on it; its protein half-life has been measured.
Gene: Protein-coding gene on chromosome 16 (74,871,362 to 75,000,173, reverse strand). Ensembl gene ENSG00000103091.
Subcellular location: Lysosome membrane
Subcellular location (Human Protein Atlas): Cytosol; Vesicles
Pathways (Reactome):
Cellular responses to stimuli: Amino acids regulate mTORC1
Gene Ontology:
Molecular function: protein binding; signaling adaptor activity
Biological process: cellular response to amino acid starvation; cellular response to nutrient levels; positive regulation of TORC1 signaling; protein localization to plasma membrane; negative regulation of TORC1 signaling
Cellular component: GATOR2 complex; lysosomal membrane; Seh1-associated complex; vacuolar membrane
Genetic constraint (gnomAD): Loss-of-function variants: 97 observed, 126.95 expected, observed/expected ratio (o/e) 0.76, 90% interval 0.65 to 0.9. The synonymous counts are far from expectation, so gnomAD's model fits this gene poorly and the ratio says little. Missense variants: 1,181 observed, 1,266.8 expected, observed/expected ratio (o/e) 0.93, 90% interval 0.89 to 0.98. Synonymous variants: 589 observed, 474.18 expected, observed/expected ratio (o/e) 1.24, 90% interval 1.16 to 1.33.
Homologues: Orthologues: chimpanzee WDR59 (99% identical), rabbit WDR59 (98% identical), dog WDR59 (97% identical), pig WDR59 (97% identical), rat Wdr59 (97% identical), mouse Wdr59 (96% identical), macaque WDR59 (96% identical), guinea pig WDR59 (93% identical), tropical clawed frog wdr59 (81% identical), zebrafish wdr59 (72% identical), Drosophila melanogaster Wdr59 (35% identical). Paralogues in human: GEMIN5 (17% identical), WDR24 (13% identical), RBBP4 (7% identical), ERCC8 (7% identical), RBBP7 (7% identical), PEX7 (6% identical), WDR73 (6% identical), GRWD1 (6% identical), WDR77 (5% identical).
Diseases named in the same sentence as WDR59 in open-access papers:
WDR59 is named in the same sentence as 5 diseases in open-access papers, as found by Europe PMC text mining. Sharing a sentence is not in itself a finding about the gene and the disease. The quoted sentences say what the papers report.
mammary tumor (1 paper, 2021). "Strikingly, individual RICTOR and WDR59 genomic deletion significantly blocked primary mammary tumor growth and reduced tumor size in NSG mice, highlighting these two proteins as potent pro-oncogenic factors." (PMID 34031411, 2021). "Here, we functionally characterized and defined important functions for mTORC2/RICTOR and GATOR2/WDR59 in controlling mammary tumor growth in TNBC." (PMID 34031411, 2021). "Importantly, activation of both RICTOR and WDR59 gene expression led to a significant increase in mammary tumor growth." (PMID 34031411, 2021). "Moreover, we identified a function for WDR59 as a potent inducer of mammary tumor growth, defining the nutrient-sensing GATOR2 complex as a pro-oncogenic pathway in TNBC." (PMID 34031411, 2021). "Our study also revealed multiple PAM signaling components as important regulators of the tumorigenic process, further defining roles for mTORC2/RICTOR and GATOR2/WDR59 in TNBC mammary tumor growth and suggesting that Sestrin3-mediated negative regulation of GATOR2 may prevent these effects." (PMID 34031411, 2021).
tumor (1 paper, 2021). "We further define novel roles for mTORC2/RICTOR and Sestrin3/GATOR2/WDR59 in promoting TNBC tumor growth." (PMID 34031411, 2021). "To further address the tumor-promoting function of RICTOR and WDR59 in the mammary gland, we used a CRISPR activation (CRISPRa) approach 43,44." (PMID 34031411, 2021). "Thus, to assess their functional relevance and contribution to TNBC tumor formation, we used a CRISPR/Cas9 KO approach to specifically block expression of one identified representative hit for each of the mTORC2 and GATOR2 complexes (RICTOR and WDR59, respectively) in the SUM159 cell line." (PMID 34031411, 2021). "Interestingly, WDR59 and RICTOR KOs showed strong decrease in rpS6 phosphorylation levels, compared with non-targeting tumor samples." (PMID 34031411, 2021). "Interestingly, three members of the GATOR2 complex (WDR59, MIOS, SEH1L) were found in our negative hits, underscoring the importance of these characterized GATOR2 components in promoting tumor growth in TNBC." (PMID 34031411, 2021).
WDR59 also shares sentences with these, for which no sentence is quoted: atherosclerosis (1 paper); breast carcinoma (1); cardiac hypertrophy (1).